IFI27 (interferon alpha inducible protein 27)
Diseases named in the same sentence as IFI27 in open-access papers (continued):
Sharing a sentence is not in itself a finding about the gene and the disease.
inflammatory myopathies (1 paper, 2023). "In addition, the IFN6 score (ISG15, LY6E, IFI44, IFI27, IFIT1, and OAS1) was higher in 13 DM patients than in 40 patients with inflammatory myopathies (no patients had SLE or MCTD)." (PMID 36979843, 2023).
kidney disease (1 paper, 2016). "Secondary renal diseases due to immunological disorders and other diseases (Groups 3 and 4) were associated with higher IFI27 mRNA level than IgAN." (PMID 27100186, 2016). "After confirming this result by quantitative real-time reverse transcription polymerase chain reaction (qRT-PCR), we extended the qRT-PCR analysis to other kidney diseases and found that IFI27 mRNA levels were reduced in PBMCs of many patients." (PMID 27100186, 2016). "We also found that IFI27 mRNA levels were reduced in the PBMCs of patients with other kidney diseases, although the reductions were less prominent than those in IgAN and MN." (PMID 27100186, 2016). "IFI27 levels in IgAN patients were significantly lower than those in patients with other kidney diseases." (PMID 27100186, 2016). "Statistical analyses confirmed that IFI27 mRNA levels were more conspicuously reduced in IgAN than in other kidney diseases." (PMID 27100186, 2016). "To determine whether expression of IFI27 protein is also reduced in patients with kidney disease, we performed IHC with an anti-IFI27 antibody on biopsied glomeruli samples from IgAN, MN, and MCNS patients." (PMID 27100186, 2016). "Because IFI27/ISG12 deficient mice show no abnormality in kidney functions, it remains unclear how these IFI27-related events are involved in the pathgenesis of kidney diseases such as IgAN and MN." (PMID 27100186, 2016).
IFI27 also shares sentences with these, for which no sentence is quoted: oral squamous cell carcinoma (5 papers); rheumatoid arthritis (5); AIDS (2); and mouth disease (2); antiphospholipid syndrome (2); Chronic Hepatitis C (2); diabetes (2); endotoxemia (2); esophageal cancer (2); esophageal squamous cell carcinoma (2); Hepatitis (2); idiopathic thrombocytopenic purpura (2); infectious disease (2); liver cancer (2); liver diseases (2); metastatic disease (2); myeloma (2); viral diseases (2); adenoma (1); Aicardi-Goutieres syndrome (1); ANCA-associated vasculitis (1); anemia (1); arrhythmogenic right ventricular cardiomyopathy (1); Arthritis (1); autoimmune disorders (1); bacterial pneumonia (1); basal cell carcinoma (1); Behçet syndrome (1); chronic hepatitis (1); connective tissue diseases (1).
A further 25 diseases each share a sentence with IFI27 in 1 paper.